SFRP4 (secreted frizzled related protein 4)
Diseases named in the same sentence as SFRP4 in open-access papers (continued):
Sharing a sentence is not in itself a finding about the gene and the disease.
tumor (85 papers, 2008 to 2025). "We then assessed stemness-associated traits—migratory capacity and tumor-initiating potential—by performing wound-healing and spheroid-formation assays following SFRP4 modulation." (PMID 40565036, 2025). "For example, SFRP4, a modulator of the Wnt signaling pathway, has been linked to tumor aggressiveness in prostate and other cancers, reinforcing its role as a candidate biomarker." (PMID 40868045, 2025). "This review aims to provide a comprehensive overview of the dualistic roles of sFRP4 in cancer, highlighting its tumor-suppressive and tumor-promoting functions, underlying molecular mechanisms, and therapeutic potential." (PMID 40891635, 2025). "Here we show that elevated tumour SFRP4 expression is associated with poor prognosis in GC which was also recently reported by others." (PMID 33277667, 2021). "Increasing SFRP4 expression was significantly linked to high Gleason grade (p < 0.0001), advanced pathological tumor stage (p < 0.0001), positive nodal status (p = 0.0002) and positive resection margin status (p = 0.0017)." (PMID 32677026, 2020). "SFRP4 upregulation was clearly linked to adverse tumor features in our study, including advanced stage, high Gleason grade, nodal metastases, rapid tumor progression (as measured by the Ki67 labeling index) and early biochemical recurrence." (PMID 32677026, 2020). "It showed that associations between SFRP4 and tumor phenotype (p ≤ 0.05 each) and PSA recurrence (p < 0.0001) were largely driven by the subgroup of cancers lacking ERG fusion." (PMID 32677026, 2020). "SFRP4 overexpression was linked to advanced tumor stage, high classical/quantitative Gleason grade (p < 0.0001 each), lymph node metastasis (p = 0.0002), and a positive surgical margin (p = 0.0017)." (PMID 32677026, 2020). "Second, a study has demonstrated that SFRP-4 induces a decrease in endothelial cell migration correlated with a reduction in tumor-associated angiogenesis in a mouse model of ovarian cancer." (PMID 31370265, 2019). "The secreted frizzled-related protein 4 (SFRP4), proposed as a tumor suppressor in many cancers based on its loss in patients’ tumors, was upregulated about 4 fold in mice treated with the combination therapy." (PMID 25127546, 2014). "Hypermethylation of the sFRP4 gene has been reported in various cancers and is associated with tumour progression and malignancy." (PMID 23039795, 2012). "Since sFRP4 is a known antagonist of the Wnt signalling pathway, its reduced expression in tumours suggests that loss of sFRP4 may contribute to Wnt pathway activation, which is linked to cancer progression." (PMID 40920763, 2025). "Among the upregulated genes in CS1, SFRP2 and SFRP4 are Wnt-regulator and can modulate the differentiation of cancer-associated fibroblasts (CAFs), which contribute to the progression and metastasis of the tumor." (PMID 38549156, 2024). "It is possible that the anti-tumour activity of sFRP4 in vitro maybe associated with inhibition of the insulin/IGF-1 pathway through AMPK activation." (PMID 29385093, 2018). "Loss of SFRP4 expression has been linked to tumor progression in pancreatic tumors." (PMID 29371979, 2017). "SFRP4 was also recently found to up-regulated in tumor-associated stromal cells." (PMID 20021671, 2009). "Therefore, secreted proteins like SFRP4 with a 12-fold increase in expression in tumor-associated stroma could potentially serve as markers for the presence of cancer." (PMID 19737398, 2009). "In conclusion, sFRP4 exerts dual roles in tumorigenesis, acting either as a tumor suppressor or promoter depending on tissue type, tumor microenvironment, and regulatory mechanisms." (PMID 40891635, 2025). "Findings demonstrate that sFRP4 frequently acts as a tumor suppressor by sequestering Wnt ligands, suppressing cancer stem cell-like properties, reprogramming tumor metabolism, inhibiting angiogenesis, and enhancing chemosensitivity." (PMID 40891635, 2025).
tumor (continued). "The potential of Silibinin and isotretinoin to upregulate the tumour suppressor sFRP4 was further examined using ELISA and real-time quantitative PCR." (PMID 40920763, 2025). "Next, we examined the location of the expression for two marker genes—EPCAM, which is a marker of malignant cells, and SFRP4, which is more highly expressed in the adjacent tumor microenvironment." (PMID 40954301, 2025). "Silencing of SFRP4 gene in pathological states results in the activation of Wnt signaling which in addition to promoting tumor evolution also leads to the inhibition of apoptosis of tumor cells." (PMID 38993819, 2024). "The results of this study should help sFRP4 become a more effective CSC inhibitor in a variety of tumor types." (PMID 39272862, 2024). "The Kruscal-Wallis test revealed a significant difference in the expression level of SFRP4 protein regarding tumor grade (p = 0.008), and the Spearman test also confirmed a moderate negative correlation between the analyzed variables (rs = −0.442, p = 0.001)." (PMID 38993819, 2024). "In the bulk sequencing data, we stratified the tumor samples into two groups according to the median expression of the marker genes (SFRP4, CLU, OGN)." (PMID 38686196, 2024). "We found that CAF subtypes 0 (BTG1+ CAF), 2 (CFD+ CAF), and 4 (IGFBP7+ CAF) were more abundant in the tumor than the normal, while CAF subcluster 1 (OGN+ CAF), 3 (C1R+ CAF), 5 (MFAP5+ CAF), and 6 (SFRP4+ CAF) were more abundant in the normal than the tumor." (PMID 38686196, 2024). "This is particularly true when it comes to SFRP4 where there is a mismatch between cell culture and human tumor tissues." (PMID 39511287, 2024). "Using scRNA-seq, we discovered a new CAF subtype, SFRP4+ CAFs, that was more common in normal than tumor samples and inhibited BC cell migration by secreting SFRP4." (PMID 38686196, 2024). "A significant difference between expression levels of SFRP4 protein regarding tumor grade (p = 0.008) was established." (PMID 38993819, 2024). "It is necessary to keep in mind that astocytomas harbor great heterogeneity and the tumor can consist of heterogeneous cells - some harboring methylated and some unmethylated promoters of SFRP4 gene." (PMID 38993819, 2024). "We first investigated the relationship between the infiltration abundance of lymphocytes in the tumor and SFRP4 expression levels." (PMID 35847366, 2022). "A significant relationship was found between SFRP4 and clinicopathological characteristics such as pathological type, tumor size, N stage, M stage, and TNM stage." (PMID 35847366, 2022). "In differently reactivated genes, SOCS3 and SFRP4 as potential tumor suppressor genes, were noted in PJ-34 and 5-aza-dC treatments, respectively." (PMID 36077707, 2022). "SFRP4 tumour expression was previously reported as part of a 6-gene signature which was able to predict recurrence of GC." (PMID 33277667, 2021). "FBN1, HIC1, and SFRP4 were lower in the tumor than normal tissues; the expressions of other ERGs were the opposite." (PMID 35095892, 2021). "The same data set has been interrogated in this study and has identified secreted frizzled-related protein 4 (SFRP4) as a gene highly correlated with tumour invasion or T-stage." (PMID 33277667, 2021). "The expression of SFRP2, SFRP3, and SFRP4 in patients with GC significantly correlated with the clinical tumor stage." (PMID 34205081, 2021). "Another antagonist of Wnt signaling is SFRP4, which belongs to the secreted frizzled-related protein family and is frequently silenced in ccRCC tumor tissues." (PMID 34657130, 2021). "Since Wnt signalling promotes glycolysis and tumour growth, we investigated the effect of the Wnt antagonist secreted frizzled-related protein 4 (sFRP4) on CSC metabolism." (PMID 29385093, 2018). "The only gene to have a positive correlation coefficient was BAD, indicating the pro-apoptotic capacity of sFRP4 in cancer metabolism in both the tumours examined." (PMID 29385093, 2018).
tumor (continued). "We show that only SFRP1 associates consistently with tumour suppressive functions, and that SFRP2 and SFRP4 typically associate with a poor prognosis concomitant with the expression of genes associated with epithelial-to-mesenchymal transition." (PMID 28218291, 2017). "In order to gain further insights into the chemo-sensitization of CSCs, we investigated the role of sFRP4 when used in combination with the chemotherapeutic drugs doxorubicin and cisplatin on CSCs derived from various tumor cell lines." (PMID 28536422, 2017). "In fact, SFRP2 and SFRP4 expression is often increased in tumours and are tightly correlated to Stromal Scores, suggesting that their expression is produced by the tumour stroma." (PMID 28218291, 2017). "Studies describing SFRP4 levels in blood are rare; most groups analyzed SFRP4 on the cellular level or within tumor tissues, supporting the function of SFRP4 as tumor suppressor gene." (PMID 25408147, 2014). "In contrast, a number of genes described as tumor suppressors (among them osteoglycin, dermatopontin and secreted frizzled-related protein 4) were significantly upregulated after combination therapy." (PMID 25127546, 2014). "Methylation of SFRP4, WIF1 and WNT5a genes were meaningfully associated with increasing tumor stage (p = 0.004, p = 0.029 and p = 0.004)." (PMID 25107489, 2014). "Comparison of sFRP4 expression in tumour biopsies revealed a positive trend between sFRP4 expression and tumour grade, with mucinous cyst adenocarcinomas exhibiting significantly decreased sFRP4 levels compared to mucinous borderline tumours." (PMID 23039795, 2012). "An inverse trend was observed for β-catenin, with benign tumours expressing significantly decreased levels of β-catenin compared to the corresponding sFRP4 expression (p < 0.001)." (PMID 23039795, 2012). "The methylation of the same genes was also associated with tumor stage RUNX3 (p = 0.040), SCGB3A1 (p = 0.032), SFRP4 (p = 0.033), and DLC1 (p = 0.035)." (PMID 20849603, 2010). "Compared to normal breast tissue, initial tumours had a much lower median expression of sFRP4." (PMID 40920763, 2025). "In addition, previous studies have reported that FBN1 and SFRP4 act as tumor suppressor genes, supporting our results." (PMID 41020879, 2025). "In addition, student’s t-test showed a significant connection between the age of tumor occurrence and the methylation of SFRP4 gene promoters (p = 0.011)." (PMID 38993819, 2024). "The consensus has been that SFRP4 is a tumor suppressor by inhibiting the oncogenic Wnt-pathway." (PMID 39511287, 2024). "SFRP4 may affect tumor growth by altering the tumor immune microenvironment and might be a potential therapeutic target for immunotherapy." (PMID 35847366, 2022). "We sought to determine whether SFRP4 levels changed after curative resection when compared to an individuals baseline level to test the change in SFRP4 level as a biomarker of tumour recurrence." (PMID 33277667, 2021). "Increased SFRP4 protein expression was observed in T3 compared with T1/T2 tumours." (PMID 33277667, 2021). "Affymetrix array-derived data were used to determine whether tumour SFRP4 mRNA expression levels could reliably predict prognosis." (PMID 33277667, 2021). "The notion, that SFRP4 upregulation may indicate altered Wnt signaling could also explain the strong link of high SFRP4 expression with high tumor cell proliferation and 10 of 11 analyzed chromosomal deletions." (PMID 32677026, 2020). "Finding strong associations between the putative tumor suppressor gene SFRP4 up regulation and aggressive tumor behavior in clinical cancer specimens is thus not intuitive." (PMID 32677026, 2020). "Gene expression levels measured relative to the adjacent normal cortex sample revealed numerous oncogenic driver genes with >2-fold higher expression in the tumour and clone samples, including genes encoding AURKA/B, CDK4/6, FGFR1, AKT1/2, MTOR, MET, PIK3C2A, WNT5A, SFRP4, and MYC." (PMID 30736342, 2019).
tumor (continued). "Further in vivo studies may confirm the efficacy of sFRP4 in altering CSC metabolism to prevent tumour relapse and lead to tumour resolution." (PMID 29385093, 2018). "Further in vivo studies may confirm the role of sFRP4 in the chemo-sensitization of CSCs to prevent tumor relapse and lead to tumor resolution." (PMID 28536422, 2017). "Consequently, SFRP4 is expected to be a tumour suppressor, and to be downregulated in aggressive cancer." (PMID 29079735, 2017). "Mounting evidence has suggested that, as a soluble Wnt inhibitor, SFRP4 may act as a tumor suppressor." (PMID 28977937, 2017). "The untreated spheroids remained intact, whereas the combinatorial treatment of sFPR4 and chemotherapeutic drugs showed disruption of spheroids post-treatment, indicating sFRP4’s capacity to segregate the tumor spheres and allow chemotherapeutic drugs to inhibit tumor proliferation." (PMID 28536422, 2017). "Negative SFRP4 expression was significantly associated with old age, larger tumor size, regional lymph node metastasis and poor differentiation." (PMID 28977937, 2017). "The absence of SFRP4 expression was significantly associated with old age, larger tumor size, regional lymph node metastases and poor differentiation (P<0.05)." (PMID 28977937, 2017). "In addition, a significant relationship from 2 studies including 63 benign mucosal lesions and 73 normal colonic mucosa was observed between SFRP4 methylation and benign mucosal lesions (OR = 12.50, P = 0.005)." (PMID 27659069, 2016). "Through interaction and inhibition of Wnt ligand, sFRP4 exert antagonistic activity in Wnt/β-catenin pathway, suggesting that sFRP4 might be a tumour suppressor." (PMID 25844602, 2015). "Moreover, methylation frequency of SFRP4 and WIF1 genes were also significantly associated with tumor differentiation (p = 0.009 and p = 0.031)." (PMID 25107489, 2014). "When methylation values were compared within individual pairs of PN and PT samples, significantly higher methylation levels of PAPSS2 TUBG2, NTRK2, and SFRP4 were found in 60% (18/30), 50% (15/30), 30% (9/30), and 36% (11/30), respectively, in PN than in corresponding tumor samples (PT)." (PMID 19662090, 2009). "There are reports that sFRP4 plays a role in tumor suppression via the Wnt pathway, although the specific relationship remains unknown." (PMID 18217891, 2008). "In addition, we compared the expression of SFRP4+ CAF marker genes in normal and tumor samples using data from the TCGA-BRCA cohort and found that most of the marker genes of SFRP4+ CAF were significantly down-regulated in the tumor samples, which was consistent with our scRNA-seq results." (PMID 38686196, 2024). "However, Postovit and Vincent found a trend toward higher SFRP4 expression during tumor growth, which may contradict the finding that SFRP4 acts as a tumor suppressor." (PMID 35847366, 2022). "In addition, we used the TIMER database to analyze the differential expression of SFRP4 in tumor tissues, the correlation between SFRP4 expression and T-cell infiltration, and the relationship between SFRP4 and the immune microenvironment based on the TISIDB database." (PMID 35847366, 2022). "Therefore, despite the stromal contribution of SFRP2 and/or SFRP4, hypermethylation within the tumour cell compartment may still show utility as a clinical biomarker." (PMID 28218291, 2017). "Furthermore, we found that aggressive clinicopathological features such as old age, larger tumor size, poor differentiation, and especially regional lymph node metastases were associated with negative SFRP4 protein expression in PDAC." (PMID 28977937, 2017). "The enhanced apoptosis and reduction in proliferation of cancer cells seen in this study may result from a reduction of canonical Wnt signalling in the tumour compartment, as a result of modification in the stromal compartment, by sequestering Wnt ligands, due to sFRP4 secretion." (PMID 27061193, 2016).
tumor (continued). "Furthermore, results also demonstrated a positive trend between sFRP4 expression and tumour grade." (PMID 23039795, 2012). "This leads to an increase in LEF1 activity within the tumor cells, driving Malignant_EP_04 cells to undergo EMT and transdifferentiate into SFRP4+ CAFs." (PMID 40810004, 2025). "The multiplex immunohistochemistry (mIHC) results on the tumour tissue of PTC also showed that IgG was also expressed on other cells besides immune cells (CD45 as a marker), including AFCs (SFRP4 as a marker)." (PMID 38426403, 2024). "If these findings reflect the need to better define the appropriate dosing regimen and/or the expression (and secretion) by tumor cells of other phosphatonins (e.g., MEPE, FGF7, sFRP-4), it remains to be established." (PMID 37436671, 2023). "Secreted frizzled-related protein 4 (SFRP4) is a member of the SFRP family, which functions as either a tumor suppressor or a prooncogenic factor in distinct tumor types." (PMID 35847366, 2022). "Besides, SFRP4 was an important Wnt signaling antagonist, and activation of SFRP4 could lead to Wnt signaling suppression and histone modification in PCa stem cells and thereby sensitized tumor cells to chemotherapeutic drugs, enhancing cell death." (PMID 35463369, 2022). "Differential gene analysis revealed 319 genes upregulated in tumor-derived fibroblasts, such as DCN and SFRP4, and 214 genes upregulated in cancer cells, such as SPRR1B and SLURP2." (PMID 36357663, 2022). "GLI1, SFRP4 and POLE genes were previously involved in tumorigenesis with a major contribution to tumor genomic instability." (PMID 36085309, 2022). "Additional hub genes MMP13, SFRP4, ADAMTS16 and FNDC1 also significantly affect survival with their expression across tumour grades comparable to CTHRC1." (PMID 36190948, 2022). "Module-1 of the ENDCAP-C study showed that their panel of five markers (SFRP2, SFRP4, WIF1, APC1A, and APC2) was accurate in detecting pre-cancerous and invasive neoplasia and dysplasia." (PMID 34842672, 2021). "A cluster of genes that were upregulated in the tumours, compared to normal tissues were COL1A1, COL11A1, SPP1, COMP, SFRP4 and INHBA." (PMID 34824625, 2021). "Just like SFRP4, RARRES1 is downregulated in the final stage, related to the fact that it has been suggested as a tumor suppressor." (PMID 34283835, 2021). "Secreted frizzled-related protein 4 (SFRP4) controls WNT signaling and is thought to play a role for tumor aggressiveness." (PMID 32677026, 2020). "In the stage 2 analysis, five markers accurately discriminated between neoplasia and control samples with p < 0.0001 – SFRP2, SFRP4, WIF1, APC1A and APC2; with between 40% and 76% increases in geometric mean values." (PMID 30473377, 2019). "Individually silencing sFRP4, GSK3β, or TLE1 increased the tumour sphere formation and enhanced the TOP flash/FOP flash activity of antagomir-942 cells." (PMID 25844602, 2015). "MeDIP-qPCR and qPCR were performed to measure demethylation status and mRNA re-expression level of 7 tumor-suppressor genes (CCNA1, CHFR, FHIT, PAX1, PTEN, SFRP4, TSLC1) in Hela and Siha cells after silencing DNMT1." (PMID 21999220, 2011). "To date, four SFRP family genes (SFRP1, SFRP2, SFRP4 and SFRP5) and two DKK family genes (DKK1 and DKK3) have been identified as targets of epigenetic silencing in human tumours." (PMID 18283316, 2008). "Notably, some genes (e.g., MET, HSPA6, ID1, MECOM, POU2AF1, SFRP4, CDH1) exhibited expression predominantly in tumor cells and a limited number of other cell types." (PMID 40954493, 2025). "We compared normal and tumor samples and found that SFRP4+ CAFs were more abundant in normal samples." (PMID 38686196, 2024). "Decreased expression or silencing of SFRP4 resulting in Wnt-pathway overactivation leading to inhibition of tumor cell apoptosis seems common in most, if not all, human cancers." (PMID 35461390, 2022).